SESN3 (sestrin 3)
Diseases named in the same sentence as SESN3 in open-access papers (continued):
Sharing a sentence is not in itself a finding about the gene and the disease.
prostate adenocarcinoma (1 paper, 2019). "miR-708 targeted Sestrin-3 to inhibit Forkhead Box O1 (FOXO1) phosphorylation, resulting in apoptosis of prostate adenocarcinoma cells and AKT-inactivated NEPC cells, the latter of which was consistent with the progression of tumor xenografts in mice under miR-708 treatment." (PMID 31583122, 2019).
pulmonary hypertension (1 paper, 2025). Increased pressure within the pulmonary circulation due to lung or heart disorder. "In pulmonary hypertension models, SESN3 mediates FOXO1-induced autophagy and suppresses mTOR activity." (PMID 40507985, 2025).
sinusoidal obstruction syndrome (1 paper, 2021). "Conditions such as viral reactivation, drug toxicity, tumoral organ infiltration, and sinusoidal obstruction syndrome among others may result in elevated PTK2B and SESN3 concentrations." (PMID 33082554, 2021).
Skeletal muscle atrophy (1 paper, 2020). The presence of skeletal muscular atrophy (which is also known as amyotrophy). "Sesn3 encodes for Sestrin3, which has been shown to have a protective effect against skeletal muscle atrophy in the context of disuse and aging." (PMID 32629989, 2020).
type 1 diabetes (1 paper, 2025). "Our analysis suggested that SESN3 may reduce T cell expression of CD3, a co-receptor essential for T cell activation and the target of teplizumab (a monoclonal antibody approved to delay the onset of stage 3 type 1 diabetes), and CD28, a key activator of T cells." (PMID 41299435, 2025).
viral infections (1 paper, 2019). "We found multiple significant differentially expressed genes (DEGs) shared between AD/PD and viral infections including SESN3 which has a genetic association for increased AD risk." (PMID 31217489, 2019).
tumor (23 papers, 2012 to 2025). "SESN3 plays an important role in the anti-tumor process of cucurbitinoid B, and silencing SESN3 can reduce the proliferation of tumor cells and cause cell cycle G2 arrest, and promote the apoptosis induced by cucurbitinoid B." (PMID 41460862, 2025). "These evidences indicate that SESN family has a broad application prospect and value in anti-tumor and drug resistance research, but research on SESN3 is still in backward stage, and further in-depth research is needed." (PMID 41460862, 2025). "Given that mTORC1 activation is a hallmark of T-ALL, the inactivation of mTORC1 contributes to the tumor-suppressor role of SESN3 in T-ALL cells." (PMID 41275290, 2025). "The increased autophagy activity induced by highly expressed autophagy-related genes including ATG4B decreases the expression of SESN3, a novel tumor-suppressor in T-ALL through autophagy-mediated protein degradation and EGR1-regulated transcription." (PMID 41275290, 2025). "Taken together, these results strongly indicated that SESN3 plays a novel tumor-suppressor role in T-ALL possibly through its inhibition of both mTOR signaling and autophagy activity." (PMID 41275290, 2025). "DNA methylation analysis also revealed the methylation of multiple genes (FRMD6-AS2, SESN3, CYTL1, MIR4429, HIF3A, and ATP1B2) associated with tumor growth suppression." (PMID 36975488, 2023). "Regarding the SESN3 gene, recent studies have identified its role as an autophagy activator in tumor cells by repressing mTORC1." (PMID 37628602, 2023). "In contrast, SESN3 downregulation reversed the effect of miR-375 downregulation and decreased tumor proliferation." (PMID 34699320, 2021). "On the contrary, SESN3 has been suggested as a tumor-suppressor in HCC, since SESN3 deficiency promoted carcinogen-induced HCC via regulating the hedgehog pathway." (PMID 34409922, 2021). "After 13 days of xenograft growth in vivo, significant decreases in HIF-1α, FoxO1, Sesn3, MnSOD and catalase expression were exhibited by the tumours from the 2ME + As2O3 treatment group compared with the tumours from the control group." (PMID 31905813, 2019). "In addition, the methylation of FRMD6-AS2, SESN3, CYTL1, MIR4429, HIF3A, and ATP1B2, which are associated with tumor growth suppression, was also detected." (PMID 36975488, 2023). "Sestrin 3 was suggested to play a critical tumor suppressor role through multiple mechanisms, including inhibition of the hedgehog signaling, controlling regeneration of peroxiredoxins to balance reactive oxygen species (ROS) upregulation induced by oncogenic Ras." (PMID 36703207, 2023). "Additionally, the methylation of FRMD6-AS2, SESN3, CYTL1, MIR4429, HIF3A, and ATP1B2, which are associated with tumor growth suppression, was detected by DNA methylation analysis." (PMID 36975488, 2023). "HCC patients with less sestrin-3 expression had a tendency of worse survival, and sestrin-3 knock-out (KO) mice demonstrated a higher tumor burden and expression of stem markers (CD133 and CD44) compared to the wild-type group in a DEN combined with a choline-deficient high-fat diet (CD-HFD) model." (PMID 33440657, 2021). "The correlations between SESN3 expression and the tumor size and TNM staging were analyzed as well." (PMID 34409922, 2021). "Since miR-214 is frequently downregulated in PCa tissue and cells, this could lead to higher levels of SESN3 and hence increased tumor growth and EMT in PCa." (PMID 34884984, 2021). "Our study demonstrate that SESN3 is significantly down-regulated in T-ALL patient samples and acts as a novel tumor-suppressor in T-ALL, which is in line with the fact that SESN3 suppresses the growth of BCR-ABL+leukemic cells." (PMID 41275290, 2025). "Overexpression of SESN3 has been observed in LUAD and ESCA models, suggesting its potential involvement in promoting pro-tumor autophagy pathways." (PMID 37628602, 2023).
tumor (continued). "Our rescue experiments, consistently, showed that silencing of SESN3 mitigated the stimulative effects of miR-375 inhibitor on ESCC biological activities and tumor growth in vivo." (PMID 34699320, 2021). "In a small group of four patients with only skin aGvHD the mean value of SESN3 and PTK2B was 0.353 and 1.323, respectively (log SESN3/PTK2B copies/ml plasma)." (PMID 33082554, 2021). "Protein and total RNA were then extracted from each tumour and used to assess the expression levels of HIF-1α, FoxO1, Sesn3, MnSOD and catalase." (PMID 31905813, 2019). "In this study we identified up-regulation of SESN2 and SESN3 in intratumoral NK-92 cells, suggesting that the tumor microenvironment induced the expression of SESN2 and SESN3." (PMID 29163816, 2017). "The repression affects known tumor or metastasis suppressor genes, such as TRIM 29, ACVR1B, and LPAR6, and the sestrins, SESN1 and SESN3; however, in our analyses, ACVR1B, LPAR6, and sestrins were not validated by the qNPA method." (PMID 22276141, 2012). "Tumours lacking Sesn3 exhibited increased activation of Akt and Stat3, along with elevated levels of stem cell markers such as Acta2, Cd44, and Cd133." (PMID 40361504, 2025). "Although we did not observe a significant change in tumor volume (data not shown), we unintentionally found higher expression of SESN2 and SESN3 in intratumoral NK-92 cells than those in splenic and peritoneal NK-92 cells." (PMID 29163816, 2017).
cancer (9 papers, 2010 to 2025). A tumor composed of atypical neoplastic, often pleomorphic cells that invade other tissues. "Further, overexpression of SESN3 was associated with cancer-cell proliferation suppression through mTORC1, Oxidative Stress, and Autophagy pathway." (PMID 36497496, 2022). "Surprisingly, SESN3 and COL1A1, which are downregulated in GATOR1 deletions, have pro-tumorigenic activity and their overexpression in cancer is associated with cisplatin resistance." (PMID 41469472, 2025). "Based on an expression profiling tool for cancer cell lines, such as ShinyThor, H446 appears to be among the highest SESN3-expressing models." (PMID 41460862, 2025). "For example, cabazitaxel, a microtubule-binding agent used in cancer therapy, was shown to moderately reduce SESN3 expression, thereby increasing intracellular ROS levels." (PMID 40361504, 2025). "Of the antioxidant enzymes, manganese superoxide dismutase (MnSOD), catalase (CAT) and sestrin 3 (SESN3) are reported to play important roles in ROS detoxication in cancer cells." (PMID 29152111, 2017). "Since in cultured cells lacking SESN3, the proteasome was not recruited to the cytosol under stress, one may postulate that tumors in which SESN3 is knocked out will fail to withstand the metabolic stress experienced by cancer cells." (PMID 39266717, 2024).
neurological disorders (2 papers, 2014 to 2021). "In contrast, sestrin 3, which is a marker of inflammation and oxidative stress and which has been implicated in some neurological disorders, was the second most highly elevated transcript." (PMID 24092878, 2014). "Likewise, a study in a Zebra fish model expressing 91 CUG repeats, reported an upregulation of Sesn3, a marker of inflammation implicated in some neurological disorders." (PMID 33530452, 2021).
SESN3 also shares sentences with these, for which no sentence is quoted: Glucose intolerance (3 papers); neuroblastoma (2); acute graft versus host disease (1); Arthritis (1); asthma (1); astrocytomas (1); breast tumours (1); brucellosis (1); chronic obstructive pulmonary disease (1); Graves disease (1); heart failure (1); hepatocellular carcinoma (1); lymphoma (1); myasthenia gravis (1); Obesity (1); pancreatic cancer (1); primary sclerosing cholangitis (1); sarcoidosis (1); Seizure (1); transient cerebral ischemia (1).